UNC93B1 (unc-93B1 regulator of TLR signaling)
Description:
Plays an important role in innate and adaptive immunity by regulating nucleotide-sensing Toll-like receptor (TLR) signaling. Required for the transport of a subset of TLRs (including TLR3, TLR7 and TLR9) from the endoplasmic reticulum to endolysosomes where they can engage pathogen nucleotides and activate signaling cascades. May play a role in autoreactive B-cells removal.
Synonyms: Unc-93B1; UNC93; UNC93B; UNC-93B; IIAE1
Tractability: Antibody: UniProt predicts a signal peptide or a membrane-spanning region. PROTAC: ubiquitination databases record sites on it; its protein half-life has been measured.
Gene: Protein-coding gene on chromosome 11 (67,991,100 to 68,004,982, reverse strand). Ensembl gene ENSG00000110057.
Subcellular location: Endoplasmic reticulum membrane; Endosome; Lysosome; Cytoplasmic vesicle, phagosome
Subcellular location (Human Protein Atlas): Nucleoplasm
Pathways (Reactome):
Disease: UNC93B1 deficiency - HSE
Immune System: Trafficking and processing of endosomal TLR
Gene Ontology:
Molecular function: protein binding; Toll-like receptor binding
Biological process: toll-like receptor 3 signaling pathway; toll-like receptor 7 signaling pathway; toll-like receptor 9 signaling pathway; intracellular protein transport; toll-like receptor signaling pathway
Cellular component: endoplasmic reticulum; endosome; early phagosome; endoplasmic reticulum membrane; Golgi membrane; lysosome; phagocytic vesicle
Genetic constraint (gnomAD): Loss-of-function variants: 33 observed, 41.68 expected, observed/expected ratio (o/e) 0.79, 90% interval 0.6 to 1.06. The synonymous counts are far from expectation, so gnomAD's model fits this gene poorly and the ratio says little. Missense variants: 650 observed, 620.81 expected, observed/expected ratio (o/e) 1.05, 90% interval 0.98 to 1.12. Synonymous variants: 322 observed, 264.38 expected, observed/expected ratio (o/e) 1.22, 90% interval 1.11 to 1.34.
Gene-disease validity (ClinGen):
ClinGen rates the evidence that UNC93B1 causes each of these diseases.
systemic lupus erythematosus (semidominant): Moderate. An autoimmune multi-organ disease typically associated with vasculopathy and autoantibody production.
Homologues: Orthologues: chimpanzee UNC93B1 (99% identical), macaque UNC93B1 (99% identical), pig UNC93B1 (93% identical), dog UNC93B1 (93% identical), mouse Unc93b1 (91% identical), guinea pig UNC93B1 (90% identical), rat Unc93b1 (87% identical), zebrafish unc93b1 (61% identical), tropical clawed frog unc93b1 (60% identical), Drosophila melanogaster CG3078 (14% identical). Paralogues in human: UNC93A (18% identical).
Diseases named in the same sentence as UNC93B1 in open-access papers:
UNC93B1 is named in the same sentence as 58 diseases in open-access papers, as found by Europe PMC text mining. Sharing a sentence is not in itself a finding about the gene and the disease. The quoted sentences say what the papers report.
lupus (14 papers, 2013 to 2025). "To date, 25 cases with UNC93B1 pathogenic mutations have been reported, including 13 with childhood-onset systemic lupus erythematosus (SLE) and 12 with cutaneous lupus." (PMID 41103438, 2025). "Together, this work formally identifies genetic variants in UNC93B1 that can predispose to childhood-onset systemic lupus erythematosus." (PMID 38831104, 2024). "Looking more broadly in a cohort of 272 patients with lupus recruited at the Guangzhou Women’s and Children’s Medical Centre, we found that seven (P2–P8) encode UNC93B1 (c.G349T p.V117L), a highly conserved variant." (PMID 38831104, 2024). "Rare genetic variants in UNC93B1 predispose to childhood-onset lupus via TLR7/-8–IRAK1/-4, validated with a corresponding mouse model." (PMID 38831104, 2024). "Indeed, the characterization of her UNC93B1 mutation may prompt additional autoantibody testing and clinical monitoring for lupus complications such as nephritis." (PMID 38780621, 2024). "We report five families harboring rare missense substitutions (I317M, G325C, L330R, R466S, and R525P) in UNC93B1 causing systemic lupus erythematosus (SLE) or chilblain lupus (CBL) as either autosomal dominant or autosomal recessive traits." (PMID 38869500, 2024). "Generation of mouse models carrying the orthologous variants has identified novel genes causing monogenic or oligogenic SLE such as TLR7, UNC93B1, SAT1 and TNIP13–6, expanding the list of monogenic lupus causes." (PMID 40386946, 2025). "In the present study, we identify two new variants in UNC93B1 (T314A, located proximally to the TLR7 transmembrane domain, and V117L) in a cohort of east Asian patients with childhood-onset systemic lupus erythematosus." (PMID 38831104, 2024). "More recently, variants in UNC93B1 that disrupt degradative sorting of TLR7 have also been shown to cause human lupus, underscoring the importance of this pathway in human SLE." (PMID 38866437, 2024). "Homozygous UNC93B1 mutant dogs with ECLE develop a cutaneous form of lupus as juveniles at a few months of age." (PMID 34440442, 2021). "Additionally, estrogen stimulation of CD11b+ monocytes derived from C57BL/6 female mice culminated in the enhanced expression of Unc93b1, a molecular chaperone required for TLR7 activity and splenocytes from lupus-prone female mice expressed higher levels of Unc93b1 as compared to C57BL/6 controls." (PMID 39916928, 2023). "UNC93B1 expression is up-regulated in SLE patients, and it is important for the optimal production of autoantibodies in lupus-prone mice (B6-Faslpr and BXSB)." (PMID 35877846, 2022).
autoimmune disease (10 papers, 2012 to 2025). A disorder resulting from loss of function or tissue destruction of an organ or multiple organs, arising from humoral or cellular immune responses of the individual to their own tissue constituents. "Mutation of three amino acids in the UNC93B1 C-terminal tail in mice caused TLR7-dependent autoimmune disease, and a coding variant in the same region has been linked to exfoliative cutaneous lupus in dogs." (PMID 38780621, 2024). "In parallel, we identify patients with autoimmune diseases carrying germline mutations in UNC93B1 corresponding to regulatory regions identified in our screen, and we show that these mutations can drive autoimmunity when introduced into mice." (PMID 38780621, 2024). "An important implication of this work is that heterozygosity for certain coding variants of UNC93B1 is sufficient to drive autoimmune disease in mice and humans." (PMID 38780621, 2024). "We therefore think that further studies investigating the presence of genetic variants affecting the C-terminal tail of UNC93B1 in patient cohorts with other autoimmune phenotypes, including familial cases of extremely rare autoimmune disorders, are warranted." (PMID 34440442, 2021). "Altogether, our results provide a comprehensive map of the regulatory landscape of UNC93B1 and establish the relevance of this landscape for human autoimmune disease." (PMID 38780621, 2024). "Autoimmune patients are identified with coding variants in UNC93B1 that map to regions identified by the screen, and the introduction of these human variants into mice leads to TLR-driven autoimmune disease." (PMID 38780621, 2024). "Previous clues that TLR7 and TLR9 are handled differently by UNC93B1 came from experiments which showed that mice harbouring a mutant form of UNC93B1 succumbed to severe autoimmune disease due to enhanced TLR7 signalling and impaired TLR9 responses." (PMID 23426937, 2013). "Variants affecting other components of this regulatory pathway, for example, the enzymes mediating phosphorylation or ubiquitination of UNC93B1, might also contribute to autoimmune diseases." (PMID 34440442, 2021). "These two intracellular TLRs necessitate UNC93B1 for their trafficking, share sequence homology, have similar expression in certain DC subtypes and both contribute to the development of some autoimmune diseases like systemic lupus erythematous." (PMID 22916010, 2012). "The identification of patients with coding variants in TLR7 and TLR8 has established the relevance of dysregulation of these receptors for human autoimmune disease, but equivalent coding variants in UNC93B1 that alter TLR responses to self-nucleic acids have not yet been described." (PMID 38780621, 2024). "Moreover, whether disruptions in UNC93B1-mediated regulation of TLRs can drive autoimmune disease in humans is an open question." (PMID 38780621, 2024). "Based on the recent insights about UNC93B1 function and the phenotypes in UNC93B1 mutant mice and dogs, we hypothesized that genetic variants affecting the C-terminal tail of UNC93B1 might also be responsible for SLE or related autoimmune disease in human patients." (PMID 34440442, 2021). "Thus, our study describes a mechanism for differential sorting of endosomal TLRs by UNC93B1, which may explain the distinct roles played by these receptors in certain autoimmune diseases." (PMID 23426999, 2013). "However, UNC93B1 upregulation may also increase the responsiveness of TLR3, TLR7, TLR8, and TLR9 to their agonists, and conditions that lead to increased UNC93B1 expression may yield autoimmune disorders." (PMID 33597952, 2020).
Autoimmunity (9 papers, 2020 to 2025). The occurrence of an immune reaction against the organism's own cells or tissues. "Mice with this Unc93b1D34A mutation develop TLR7-dependent autoimmunity, suggesting that UNC93B1 carefully tunes levels of TLR7 to avoid responses to self-RNA." (PMID 38780621, 2024). "The p.Pro480Thr variant is predicted to affect the C-terminal tail of the UNC93B1 that has recently been shown to restrict TLR7 mediated autoimmunity via an interaction with syndecan binding protein (SDCBP)." (PMID 32028618, 2020). "Additionally, UNC93B1 variants have been linked to TLR7‐dependent autoimmunity, and the instability of the UNC93B1 protein decreases contact with TLR7 but overactivates specific TLR7 with a continuous type I IFN response in macrophages." (PMID 40491969, 2025). "Next, we generated knock-in mice using Cas9 genome editing to test directly whether the increased TLR signaling observed in cells expressing UNC93B1 coding variants is capable of driving autoimmunity." (PMID 38780621, 2024). "Binding of syntenin-1 is regulated by phosphorylation of two serine residues in the C-tail of UNC93B1 and inhibition of the UNC93B1/syntenin-1 interaction or K63-ubiquitination of UNC93B1 results in enhancement of TLR7 signaling and causes autoimmunity in mice." (PMID 35874766, 2022). "Gene-edited mice expressing a mutant Unc93B1 in which three critical amino acids of this C-terminal domain were altered (530-PKP/AAA-532) developed hallmarks of systemic inflammation and autoimmunity, similar to what has been observed in Tlr7 overexpressing mice." (PMID 32028618, 2020). "Consistent with this premise, mice lacking cGAS and Unc93B1 or STING and Unc93B1 developed minimal systemic autoimmunity as compared to cGAS or STING single knock out animals." (PMID 33854495, 2021).
herpes simplex encephalitis (8 papers, 2015 to 2024). Herpes simplex virus encephalitis (HSE) is caused by the infection of the central nervous system by Herpes simplex virus (HSV) that could have a devastating clinical course and a potentially fatal outcome particularly with delay or lack of treatment. "Autosomal recessive deficiency of UNC93B1 in humans may predispose to herpes simplex encephalitis (HSE) following herpes simplex type I virus (HSV-1) infection through insufficient production of type I (IFN-α and IFN-β) and type III (IFN-γ) interferons." (PMID 33597952, 2020). "Gene mutations in nucleic acid sensing components such as TLR3 or its downstream signaling molecules (including UNC93B1, TLR3, TRIF, TRAF3, TBK1, IRF3, etc.)are one of the causes of herpes simplex encephalitis." (PMID 38814453, 2024). "In this study, we identified 2 genetic variants in IRF7 and UNC93B1 in our proband, who had full recovery from neonatal SEM disease but had a recurrence of HSV encephalitis during infancy after stopping preventative acyclovir therapy." (PMID 37097753, 2023). "Variants in TLR3 as well as TRIF, TRAF3, TBK1, IRF3, and NEMO that code for mediators downstream of TLR3, and UNC93B1 that is involved in TLR3 trafficking, all reduce type I interferon signaling and are reported genetic causes of herpes simplex encephalitis (HSE)." (PMID 35126383, 2021).
COVID-19 (5 papers, 2021 to 2026). A disease caused by infection with severe acute respiratory syndrome coronavirus 2. "Recently, LOF variants in UNC93B1 have been associated with severe COVID-19 susceptibility, whereas GOF variants in the same gene have been shown as SLE-causing." (PMID 40423910, 2025). "It has been found that about 3.5% of COVID-19 patients had known autosomal-recessive (AR) deficiencies [interferon regulatory factor 7 (IRF7) and IFNAR1] and autosomal-dominant deficiencies (AD) [toll-like receptor 3 (TLR3), UNC93B1, TICAM1, TBK1, IRF3, IRF7, IFNAR1, and IFNAR2]." (PMID 34335535, 2021).
Immunodeficiency (5 papers, 2009 to 2025). Failure of the immune system to protect the body adequately from infection, due to the absence or insufficiency of some component process or substance. "Complete loss-of-function of UNC93B1 results in a severe immune deficiency in human patients and the 3d mouse mutant." (PMID 32028618, 2020).
viral infection (5 papers, 2012 to 2019). "Mutations in UNC93B1 in humans have led to impaired production of interferon which is necessary to fight herpetic virus infection." (PMID 24595071, 2014). "In conclusion, this study indicates that UNC93B1, which is essential for combined endosomal TLR signaling, contributes to development of effective innate immune responses to an acute virus infection in the liver." (PMID 22723955, 2012). "Mice homozygous for a nonfunctional Unc93b1 (H412R) allele (Unc93b13d/3d) fail to respond to TLR3, TLR7, or TLR9 ligands, and mice and humans deficient in UNC93B1 are highly susceptible to viral infection." (PMID 23426999, 2013).
influenza infection (3 papers, 2019 to 2024). "Another study also reported that Unc-93 homolog B1 (UNC93B1), a transmembrane protein correlated with influenza infection, plays essential roles in oral squamous cell carcinomas by regulating GM-CSF levels." (PMID 38469236, 2024).
acute myeloid leukemia (2 papers, 2023 to 2024). Acute myeloid leukemia (AML) is a group of neoplasms arising from precursor cells committed to the myeloid cell-line differentiation. "There is a close relationship between UNC93B1, IL2RA, HSPA1B, and SOCS1 overexpression and chemotherapy resistance in patients with acute myeloid leukemia (AML)." (PMID 39213256, 2024). "Together, these data indicated that high-UNC93B1 expressed AML cells shows greater dependence on MCL1 than BCL2 for survival, and UNC93B1 might be a biomarker to predicting drug response in acute myeloid leukemia." (PMID 36741319, 2023).
breast carcinoma (2 papers, 2021 to 2024). "For example, UNC93B1 promotes tumoral growth by regulating granulocyte-macrophage colony-stimulating factor secretion in human oral cancer; nonetheless, it has not yet been associated with breast cancer." (PMID 38911383, 2024).
encephalitis (2 papers, 2022 to 2023). An acute inflammatory process affecting the brain parenchyma. "This study reports an infant with recurrent HSV-1 disease complicated by encephalitis associated with deleterious variants in the IRF7 and UNC93B1 genes." (PMID 37097753, 2023).
epidermodysplasia verruciformis (2 papers, 2018 to 2019). A rare inherited genodermatosis characterized by chronic infection with human papillomavirus (HPV) leading to polymorphous cutaneous lesions and high risk of developing non melanoma skin cancer. "Examples of such diseases are TLR3, TRIF, or UNC93B1 deficiencies which predispose to HSV-1 encephalitis and epidermodysplasia verruciformis or CXCR4 deficiencies which predispose to HPV." (PMID 31191561, 2019).
heart failure (2 papers, 2015 to 2019). Inability of the heart to pump blood at an adequate rate to meet tissue metabolic requirements. "UNC93B1, the top upregulated gene lncRNA corresponded to, encodes UNC93B1 protein that is involved in innate and adaptive immune response by regulating toll-like receptor signaling and is proved to be related to left ventricular diastolic function, heart failure morbidity, and mortality." (PMID 31355260, 2019).
HIV-1 infection (2 papers, 2020 to 2025). The type species of lentivirus and the etiologic agent of acquired immunodeficiency syndrome (AIDS). "Thus, one potential mechanism for the inversion IFNβ-specific ISGs in the gut during chronic HIV-1 infection may be the IFNβ-mediated induction of UNC93B1." (PMID 33064743, 2020). "Transient knockdown of MAVS, STING, or UNC93B1 did not affect HIV-1 infection establishment, as quantified by p24Gag production in the culture supernatants, compared to non-targeted (scramble) control." (PMID 40920844, 2025).
leukemia (2 papers, 2022 to 2023). A malignant (clonal) hematologic disorder, involving hematopoietic stem cells and characterized by the presence of primitive or atypical myeloid or lymphoid cells in the bone marrow and the blood. "As we all known, AML subtype M4-with eosinophilia (M4-eo) is classified by AML blasts with inv that have a myelomonocytes with immature basophilic granules, which is consistent with our results that UNC93B1 is higher in M4/M5 FAB subtypes leukemia." (PMID 36741319, 2023). "Thus, UNC93B1 may play an integral role in this process and influence the prognosis of leukemia." (PMID 36211454, 2022).
parasite infection (2 papers, 2010 to 2018). "A deficiency in the functional UNC93B1 protein abolished TLR dependent cytokine secretion by macrophages and attenuated immune responses against intracellular parasite infection, including Trypanosoma cruzi and T. gondii." (PMID 29530077, 2018). "While this difference was not dramatic, it was consistent, suggesting that UNC93B1 may also mediate host resistance to this parasitic infection by a novel mechanism, independent of TLR function." (PMID 20865117, 2010).
Splenomegaly (2 papers, 2022 to 2024). Abnormal increased size of the spleen. "Analysis of 10-wk-old Unc93b1+/T93I animals revealed splenomegaly, and within the B cell compartment, we observed increased numbers of germinal center B cells, ABCs, and plasma cells." (PMID 38780621, 2024). "Both hemizygous founder mice died before breeding (the female died at 8 wk, the male at 10 wk), but we were able to perform gross necropsy, which revealed extreme splenomegaly in both Unc93b1T93I/- mice relative to Unc93b1+/+, Unc93b1+/−, and Unc93b1−/− littermates." (PMID 38780621, 2024).
anemia (1 paper, 2023). A reduction in the number of red blood cells, the amount of hemoglobin, and/or the volume of packed red blood cells. "Anemia is associated with increased formation of trabecular bone, like that described in DNAse2a-deficient mice in which bone accrual requires both STING and the endosomal TLR transporter Unc93b1." (PMID 37495396, 2023).
Facial palsy (1 paper, 2013). Facial nerve palsy is a dysfunction of cranial nerve VII (the facial nerve) that results in inability to control facial muscles on the affected side with weakness of the muscles of facial expression and eye closure. "Attempt to study the blood DNA for UNC-93B1 gene mutations predisposing to herpes virus infection in patients of MRS with facial palsy yield no results." (PMID 24225172, 2013).
familial chilblain lupus (1 paper, 2025). An instance of Chilblain lupus that is caused by an inherited modification of the individual's genome. "While UNC93B1 p.Ile317Met (c.325G >C) associates with gain of TLR7 activity and jSLE, UNC93B1 p.Leu330Arg, p.Arg466Ser, and p.Arg525Pro primarily associate with gain of TLR8 activity, isomorphic TLR7 activity and familial chilblain lupus." (PMID 41410901, 2025).